IL17A (interleukin 17A)
Diseases named in the same sentence as IL17A in open-access papers (continued):
Sharing a sentence is not in itself a finding about the gene and the disease.
allergic asthma (121 papers, 2010 to 2026). A asthma with a basis in a pathological type I hypersensitivity reaction. "The evidence suggests that the IL-6/IL-17A axis is associated with fungal allergic asthma in conditions with B cell deficiency." (PMID 35740474, 2022). "For example, in a JH−/− (B cell-deficient) murine model of fungal allergic asthma, levels of the inflammatory cytokines IL-6 and IL-17A were significantly elevated, and there was significantly more robust airway eosinophilia and neutrophilia." (PMID 35740474, 2022). "TLR3 activation by poly (inosinic-cytidylic) acid in an established experimental allergic asthma mice model increased the release of proinflammatory cytokines and mucus production which was also associated with increased production of IL-17A by NK cells." (PMID 34394070, 2021). "Secretion of both IL-5 and IL-17A is elevated in allergic asthma which is associated with eosinophilic and neutrophilic endotypes, respectively." (PMID 29228740, 2017). "It has been shown that IL-17A causes neutrophilic inflammation in allergic asthma via IL-8 as both IL-17A and IL-8 mRNA are increased in the sputum of allergic patients." (PMID 22855687, 2012). "TLR3 activation in an established experimental allergic asthma mice model increased the release of proinflammatory cytokines and mucus production which was also associated with the increased production of interleukin 17 (IL-17A) by natural killer (NK) cells." (PMID 34394070, 2021). "Our study suggests that Sema3E could be considered as a novel treatment for chronic allergic asthma via regulation of both Th2, e.g. IL-4 and IL-5, and Th17, e.g. IL-17A, associated cytokines." (PMID 29228740, 2017). "However, human studies are needed to gain deeper insight into the immunological and pathogenic role of IL-17A in allergic asthma." (PMID 22855687, 2012). "Here, using a murine model of allergic asthma we report compromised fear extinction in mice with severe but not mild airway inflammation (AI); an effect abolished by anti-interleukin-17A (IL-17A) antibodies." (PMID 41646359, 2026). "In mice, delayed microbial maturation increased TH17-frequency and led to IL-17A dependent aggravated allergic asthma, even with allergen exposure at the time of normalized microbial diversity." (PMID 40443663, 2025). "Herjan and colleagues have shown that the IL17A treatment of airway smooth muscle cells can reduce CCL11 expression in a mouse model of allergic asthma." (PMID 39108259, 2024). "It has been demonstrated by others that IL-17A application can induce neutrophilia in murine allergic asthma." (PMID 37443808, 2023). "IL-17A is upregulated in allergic asthma patients, and the upregulation of IL-17A is correlated with the severity of allergic asthma." (PMID 35211018, 2022). "IL-17A plays a key role in neutrophil response in the lung; IL-17A is involved in the pathogenesis of allergic asthma and airway remodeling and induces neutrophil infiltration." (PMID 33806085, 2021). "Further, BHT down-regulated expression levels of pro-inflammatory cytokines, such as TNF-α, IL-1β, IL-6, IL-8 and IL-17A indicating that BHT has an effect on declining pro-inflammatory response for allergic asthma." (PMID 32397290, 2020). "IL-17A is also involved in numerous aspects of the pathogenesis of allergic asthma and airway remodeling." (PMID 30823378, 2019). "There is a report that IL-17A contributes to neutrophil infiltration in airway inflammation in allergic asthma." (PMID 24982682, 2014). "We observed that the percentage of CD4+ IL-17A+ T cells was higher in allergic asthma patients than in healthy controls (P = .02)." (PMID 23822853, 2013). "This study shows for the first time that increased levels of IL-17A are involved in the systemic and upper and lower airway inflammation in children with allergic asthma and rhinitis." (PMID 23573194, 2013).
allergic asthma (continued). "In conclusion, we have demonstrated that Th17 cells producing IL-17A are more frequently observed in allergic asthma and rhinitis in children, showing a role in the systemic and local inflammation, reinforcing the concept of the “united airway disease”." (PMID 23573194, 2013). "OVA-induced allergic asthma increased the levels of Inf-γ (Th1 cytokine), Il-4 and Il-13 (Th2 cytokines), and Il-17a (Th17 cytokine) mRNAs in BALF cells, whereas the administration of empagliflozin or canagliflozin administration reduced the extent of these increases." (PMID 39062810, 2024). "In combination with allergic asthma, IL-17A induced a strong neutrophilia." (PMID 37443808, 2023). "Our final conclusion is that TLR9 may be an effective therapeutic target in HDM-induced allergic asthma: treatment with anti-TLR9 inhibitory antibody abruptly increased IL-17A production by interfering with the TLR9–IL-2 axis." (PMID 33093516, 2020). "The production of IL-17A is negatively regulated by the anaphylatoxins, and C3a signaling elevates Th17 responses, while C5a signaling suppresses Th17 cell differentiation in experimental allergic asthma." (PMID 30405606, 2018). "We thus speculate that E. granulosus infection may decrease the severity of allergic asthma by enhancing IL-10 expression and down-regulating the expression of IL-17A." (PMID 25409540, 2014). "We has established a regulatory role for IL-17A and IL-22 in allergic asthma." (PMID 23738146, 2013). "IL-17A contributes to neutrophil infiltration in the airway inflammation of allergic asthma." (PMID 23731974, 2013). "In addition, IL17A could regulate DC migration to the peribronchial lymph nodes and allergen presentation in experimental allergic asthma." (PMID 33868246, 2021). "Next, we examined whether IL-17A would suppress the pathology of HDM-induced allergic asthma." (PMID 33093516, 2020). "Furthermore, showing higher levels of intracellular IL-17A and RORγ(t), associated with lower levels of Foxp3 in T-lymphocytes, together with higher plasma levels of IL-17A we suggests that there is a Th17/Treg imbalance toward Th17 cells in moderate forms of allergic asthma and rhinitis." (PMID 23573194, 2013). "Additional studies indicate that enhanced IL-17A levels correlate with increased AHR in asthmatics and allergic asthma in mice." (PMID 25816135, 2015). "Several studies have shown that IL-17A is up-regulated in lung tissues, BALF, sputum, and peripheral blood from patients with allergic asthma." (PMID 22855687, 2012). "Therefore, we induced allergic asthma with OVA, challenged mice several times, and applied IL-17A intranasally during provocation." (PMID 37443808, 2023). "IL17A, IL33, and IFNγ levels were significantly elevated in allergic and nonallergic asthmatics when compared to control, whereas IL5 levels were elevated only in patients with allergic asthma when compared to control." (PMID 30306094, 2018). "We found that IL-17A does not influence the TH2 response, but it induced neutrophilia only when allergic asthma was induced." (PMID 37443808, 2023). "In addition, it has been shown that murine neutrophils release IL-17, but no further studies have investigated the expression and release of IL-17A -the most common form of IL-17- from human peripheral blood neutrophils in neither a normal state or during disease ( e.g., allergic asthma)." (PMID 23822853, 2013).
spondyloarthritis (121 papers, 2011 to 2026). "The objective of this research was to evaluate the diagnostic accuracy of salivary interleukin (IL)-17A for temporomandibular joint (TMJ) internal derangements (IDs) in patients with spondyloarthritis (SpA)." (PMID 41751323, 2026). "Interleukin-17A (IL-17A) plays a pathogenic role in several rheumatic diseases including spondyloarthritis and, paradoxically, has been described to both promote and protect from bone formation." (PMID 27165410, 2016). "Several lines of evidence support IL-17A as a pathogenic factor that contributes to the inflammatory response in spondyloarthritis and as a promising therapeutic target in rheumatic disease." (PMID 27165410, 2016). "In addition to DKK1, the dual blockade of TNF and IL-17A was reported to ameliorate inflammation and structural damage in a rat model of spondyloarthritis, suggesting that TNF and IL-17A have pathogenic effects on bone metabolism." (PMID 37798786, 2023). "Secukinumab targets IL-17A and has demonstrated significant efficacy in managing spondyloarthropathies, including PsA, axSpA, and PsO, and it is accompanied by a favorable safety profile, characterized by a limited incidence of severe adverse events." (PMID 40076933, 2025). "Considering spondyloarthritis patients as a group with shared pathophysiological characteristics, both had higher IL17A gene expression." (PMID 36997896, 2023). "Secukinumab is a human monoclonal antibody able to inhibit IL-17A, a cytokine with a key role in promoting chronic inflammation and consequent tissue damage in spondyloarthritis." (PMID 36451402, 2022). "Interleukin 17A (IL-17A) is a cytokine with a key role in promoting chronic inflammation and consequent tissue damage in spondyloarthritis." (PMID 36451402, 2022). "IL-17A and IL-17F together with their coreceptor (IL-17RA/RC) were reported to play a significant role in the pathogenesis of spondyloarthritis." (PMID 34744511, 2021). "More recently, IL-17F has been proposed to contribute beyond IL-17A in the pathobiology of both inflammation and new bone formation in spondyloarthritis." (PMID 33679714, 2020). "IL-17A is a central driver of spondyloarthritis (SpA), its production was originally proposed to be IL-23 dependent." (PMID 30038617, 2018). "Here we show increased numbers of GM-CSF-producing CD4 and CD8 lymphocytes in the blood and joints of patients with spondyloarthritis, and increased numbers of IL-17A+GM-CSF+ double-producing CD4, CD8, γδ and NK cells." (PMID 29142230, 2017). "Murine models of inflammation suggest that co-expression of GM-CSF and IL-17A by CD4 T cells marks out a pathogenic subset of Th17 cells, and neutralisation of GM-CSF in the Sagakuchi model of spondyloarthritis causes improvement in joint inflammation." (PMID 29142230, 2017). "We purified ex vivo CD4 IL-17A+ cells by single cytokine capture from 4 spondyloarthritis, 4 RA and 3 healthy controls." (PMID 29142230, 2017). "Spondyloarthritis encompasses a group of common inflammatory diseases thought to be driven by IL-17A-secreting type-17 lymphocytes." (PMID 29142230, 2017). "Both GM-CSF+ and IL-17A+GM-CSF+ double-producing CD4 T cells express increased levels of GPR65, a proton-sensing receptor associated with spondyloarthritis in genome-wide association studies and pathogenicity in murine inflammatory disease models." (PMID 29142230, 2017). "Blockade of IL-17A or IL-17RA is a promising therapeutic approach in patients with spondyloarthritis, as it decreases IL-17-induced inflammation." (PMID 27165410, 2016). "Given the onset of spondyloarthritis with axial and peripheral presentation in a patient treated with adalimumab for relapsing anterior uveitis, we decided to change the therapeutic strategy by inserting an IL-17A inhibitor drug." (PMID 36451402, 2022).
spondyloarthritis (continued). "We assessed the effects of 5 weeks of dual blockade of TNF and IL-17A, TNF inhibitor monotherapy, and IL-17A inhibitor monotherapy, compared to vehicle control, on the severity and the extent of spondyloarthritis manifestations in the M. tub.-induced HLA-B27/huB2m tg rats." (PMID 35055042, 2022). "In this study, we hypothesized that the dual blockade of TNF and IL-17A would effectively reduce both inflammation and structural damage in the context of spondyloarthritis." (PMID 35055042, 2022). "IL-17A plays a major role in the pathogenesis of spondyloarthritis (SpA)." (PMID 34552583, 2021). "Furthermore, the secretion of IL-17A and TNF-α contributes to the bone loss observed in spondyloarthropathies." (PMID 32707785, 2020). "Importantly, we here show that the percentage of IL-17A+GM-CSF+ double-positive cells is greatly increased in the peripheral blood of patients with spondyloarthritis, with further increases in the ex vivo synovial fluid." (PMID 29142230, 2017). "IL-17A+ CD4 cells (Th17 cells) were increased in spondyloarthritis compared to both control groups." (PMID 29142230, 2017). "If IL-17A protects against bone formation by inhibiting osteoblast maturation, blocking IL-17A may potentially be detrimental for patients with spondyloarthritis by promoting and exacerbating bony overgrowth." (PMID 27165410, 2016). "As IL-17A inhibits calvarial osteoblast differentiation, we propose that IL-17A may play a role in limiting bone formation at inflamed periosteal sites in spondyloarthritis." (PMID 27165410, 2016). "As ILC3s are enriched in spondyloarthritis synovial tissue, production of IL-17A and IL-17F by these cells could offer an explanation as to why ustekinumab, which targets the p40 subunit common to both IL-12 and IL-23, was also not efficacious in axial spondyloarthritis." (PMID 33329560, 2020). "IL-17A may limit the extent of bone formation at inflamed periosteal sites in spondyloarthritis." (PMID 27165410, 2016). "We used Boolean gating to delineate the functional overlap of IL-17A, IFN-γ and GM-CSF production by CD4 T cells in healthy controls, spondyloarthritis and RA." (PMID 29142230, 2017). "IL-17A+GM-CSF+ cells were also increased in CD8, γδ and CD56+ lymphoid subsets in spondyloarthritis." (PMID 29142230, 2017). "Thus, it is important to understand the impact of IL-17A on bone in an inflammatory setting, with specific attention paid to its effect on bone formation at periosteal and enthesial sites, as this can lead to significant morbidity and disability in spondyloarthritis patients." (PMID 27165410, 2016). "However, both IL-17A−GM-CSF+ CD4 cells and double-positive IL-17A+GM-CSF+ CD4 and CD8 cells were markedly increased in spondyloarthritis synovial fluid relative to blood." (PMID 29142230, 2017). "In endoscopic mucosal samples, IBD similarly exhibits a strong TH1 phenotype in early lesions and switches to a TH17 phenotype, with marked increase in IL-17A, and induction of IL-6 and IL-23; it can occur subsequent to different categories of JIA as well as spondyloarthropathies." (PMID 28288653, 2017). "Our finding that periosteal bone formation is increased in the absence of IL-17A in an inflammatory environment stresses the need for additional studies of the interplay between IL-17A, control of inflammation, and bone formation in spondyloarthritis." (PMID 27165410, 2016).
malaria (120 papers, 2009 to 2026). Malaria is a serious and sometimes fatal disease caused by a parasite that commonly infects a certain type of mosquito which feeds on humans. "The SNPs were analysed among individuals concerning malaria disease status to detect their influence on the IL-17A serum levels and its potential associations with malaria severity." (PMID 38438955, 2024). "We have determined the serum IL-17A levels and genotyped IL-17A variants in Senegalese severe and uncomplicated malaria patients and controls." (PMID 38438955, 2024). "We performed a multivariate regression to estimate the impact of human IL-17A variants on IL-17A serum levels and malaria outcomes." (PMID 38438955, 2024). "We aimed to investigate IL-17A serum levels in patients with severe and uncomplicated malaria and gene polymorphism’s influence on the IL-17A serum levels." (PMID 38438955, 2024). "Our results fill a gap in the implication of IL-17A gene polymorphisms on the cytokine level in a Senegalese malaria cohort." (PMID 38438955, 2024). "Our results fill a gap in the implication of IL-17A gene polymorphisms on the cytokine level in a malaria cohort." (PMID 38438955, 2024). "High levels of IL-17A have been implicated in severe malaria anemia, multiple organ dysfunction, including acute renal failure during severe malaria." (PMID 37525227, 2023). "Single Nucleotide Polymorphisms (SNPs) in encoding regions of the IL-17A gene may influence changes in its expression and, potentially, malaria pathogenesis and risk." (PMID 38438955, 2024). "Then, statistical IL-17A polymorphism analysis was performed using logistic regression to test whether polymorphisms were associated with malaria severity." (PMID 38438955, 2024). "IL-17A gene polymorphisms also may influence cytokine production in response to Plasmodium infections and may be contribute to the hyperinflammatory responses during severe malaria outcomes." (PMID 38438955, 2024). "IL-17A gene polymorphisms also may influence cytokine production in response to Plasmodium infections and may contribute to the hyperinflammatory responses during severe malaria outcomes." (PMID 38438955, 2024). "In addition, Increasing levels of IL-17A have been associated with inflammation in malaria and mediating protection in various infectious diseases through the recruitment of immune cells such as neutrophils and mediate the production of several pro-inflammatory cytokines." (PMID 33281757, 2020). "Indeed, it has been shown in mouse models of malaria that IL-17A may have a protective role since such infected IL-17 deficient mice had higher levels of parasitemia and shortened survival rates." (PMID 25889652, 2015). "The current report revealed an elevated level of IL-17A in severe malaria patients compared to healthy controls in Senegalese cohort." (PMID 38438955, 2024). "We found an elevated level of IL-17A in severe malaria patients who were survivors compared to those who were deceased." (PMID 38438955, 2024). "IFN-γ and IL-17A levels have been found to be negatively correlated with PM infection and maternal anaemia, and an association of IFN-γ with protection from malaria has been reported." (PMID 33422078, 2021). "Here, we characterized EBNA1-specific IFN-γ, IL-10 and IL-17A T cell responses in eBL children compared to healthy children residing in malaria holoendemic (Kisumu) and hypoendemic (Nandi) regions of Kenya to gain further insights into eBL immunopathology." (PMID 34771539, 2021). "Intracellular cytokine production (IFN-γ, TNFα, IL2, and IL17A) from PBMC stimulated with pooled malaria and schistosoma antigens was measured in 24 SP Mal and 24 SN Mal children (n = 48)." (PMID 29449839, 2017). "IL-17A production was measured in the acute malaria stage with expression being significantly reduced at the dry season follow-up." (PMID 29449839, 2017).